MTOR (mechanistic target of rapamycin kinase)
Diseases named in the same sentence as MTOR in open-access papers (continued):
Sharing a sentence is not in itself a finding about the gene and the disease.
epilepsy (continued). "A retrospective study of mTOR inhibitor treatment in patients with TSC under the age of 2 years (n = 17) found everolimus to be efficacious and safe for infants with cardiac rhabdomyoma, SEGA and epilepsy." (PMID 34632383, 2021). "Much of the current evidence for the utility of mTOR inhibitors in the treatment of non-TSC epilepsy is still in the pre-clinical phase." (PMID 33643212, 2021). "mTOR, a ubiquitous 289 kDa serine/threonine kinase in the phosphatidylinositol 3-kinase (PI3K)-related kinases (PIKK) family, is dysregulated in a number of human diseases, including tuberous sclerosis complex (TSC) and epilepsy." (PMID 33643212, 2021). "While elevated MTOR activity is known to be epileptogenic, our data suggest that alternate PI3K-AKT targets acutely regulate neuronal hyperactivation in PIK3CA-driven epilepsy." (PMID 34899181, 2021). "While timing appears to be an important factor to control the symptoms, such as the neurological sequelae of early epilepsy, some effects do not appear to depend strongly on age, e.g., the effect of mTOR inhibition on seizures." (PMID 34298906, 2021). "Mechanistic target of rapamycin (mTOR) inhibitor treatment for epilepsy alone was not a cost-effective treatment strategy based on the costs induced by the mTOR therapy in the historic reports, given at USD 134,436/year (range USD 142,737–160,462)." (PMID 31964424, 2020). "The findings discussed here suggest that mTOR-dependent autophagy and UPS play a key role in epilepsy by producing plastic changes in the brain which may partially overlap with those responsible for neuroprotection against excitotoxicity." (PMID 32121250, 2020). "Osthole may be useful in the treatment of epilepsy and other neurodegenerative diseases that are characterized by over expression of PI3K/Akt/mTOR." (PMID 30922159, 2019). "Epilepsy is a prevalent feature of TSC and the mTOR pathway plays major roles in epileptogenesis." (PMID 31053163, 2019). "This retrospective multicenter study demonstrates that mTOR inhibitor treatment with everolimus is safe in TSC patients under the age of 2 years and shows beneficial effects on cardiac manifestations, SEGA size and early epilepsy." (PMID 31053163, 2019). "The mTOR pathway regulates a large number of cellular processes, and mTOR hyperactivation occurs in TLE patients and in several experimental models for epilepsy." (PMID 30037344, 2018). "Timing of mTOR inhibition may be important—early treatment with rapamycin decreases mTOR activation, decreases glial proliferation, increases GLT1 expression, prevents epilepsy, and increases survival." (PMID 28367137, 2017). "mTOR inhibitors have also been shown to be effective in the treatment of a number of other manifestations of TSC including renal angiomyolipoma, lymphangioleiomyomatosis, and epilepsy." (PMID 27502586, 2016). "Moreover, a recent study shows over-activation of IL-1β signaling pathway in astrocytes before epilepsy onset in a mouse model of TSC, pointing to the role of mTOR-mediated inflammatory mechanisms in TSC." (PMID 27122151, 2016). "mTOR inhibitors, administered as monotherapy or in combination, have been proposed as disease-modifying agents for TSC-related epilepsy and ISs, although their long-term use is limited by adverse effects and by the observation that the antiepileptic response may wane over time." (PMID 41470225, 2025). "However, dysregulation of BDNF in epilepsy is not a single entity but is related to the dysregulation of autophagy, mTOR pathway, PGN and α-Syn which negatively and positively regulate the BDNF/TrkB signaling pathway." (PMID 38006577, 2024). "Future studies are needed to evaluate Pten-negative and whether this correlates with the levels of mTOR hyperactivity and epilepsy severity." (PMID 37880579, 2023).
epilepsy (continued). "In animal models of epilepsy, inhibition of mTOR reduces mossy fiber sprouting but does not reduce ectopic hilar neurons, suggesting that mislocalization of newborn neurons to the HL may be regulated through other pathways." (PMID 34095131, 2021). "There are some small clinical trials looking at mTOR inhibitors in non-TSC epilepsy." (PMID 33643212, 2021). "Yet, these treatments remain effective only to a modest degree, suggesting that MTOR activation may not be the sole arm of this complex signaling pathway accounting for all PI3K pathway-driven epilepsies." (PMID 34899181, 2021). "Finally, a recent study on a TSC/mTOR-dependent epilepsy mouse model has shown that VGB does not prevent epilepsy but significantly delays the onset of seizures and lowers their frequency." (PMID 34833089, 2021). "However, there are still limited data on the use of mTOR inhibitors for the treatment of non-TSC epilepsy." (PMID 33643212, 2021). "Finally and most importantly, mTOR inhibition as therapy of TSC could potentially be extrapolated to other genetic and acquired epilepsies." (PMID 33041976, 2020). "Intriguingly, overactivation of the mTOR pathway in mouse mature microglia in vivo leads to less-ramified microglia, increased proliferation and robust phagocytic activity in the absence of an inflammatory response in a mouse model of epilepsy." (PMID 32611604, 2020). "This could be supported by a recent report that DEPDC5, as a single mTOR gene, is a key contributor to a broad spectrum of lesional and non-lesional epilepsies, with variable but highly consistent phenotypes." (PMID 31875159, 2019). "MTOR is therefore also a candidate gene for epilepsy without cortical malformation." (PMID 31780880, 2019). "Our findings demonstrate that mTOR pathways also control CRMP-2 and synaptic protein expression in in vivo epileptic rat brain tissues, as seen in cultured neuronal cells, and therefore imply the potentially important role of CRMP-2 regulated by mTOR in epilepsy." (PMID 28966575, 2017). "Therefore, epilepsy in these mice occurs without requiring the presence of a tuber or other macroscopic structural lesion, suggesting that alteration of the mTOR pathway itself is sufficient to generate seizures." (PMID 28367137, 2017). "Since brain injury is associated with changes in IGF-1 signaling, and one of the downstream effectors of IGF-1 signaling, mTOR pathway, is involved in epileptogenesis, it is possible that neuroprotective levels of IGF-1 may play a role in the development of epilepsy." (PMID 27561791, 2016). "Overall, nine of our eleven autism subjects, regardless of whether they had concurrent seizure disorder, exhibited decreases throughout the mTOR pathway." (PMID 25627160, 2015). "In addition, activation of mTOR pathway increases the expression of LDH by activating STAT3, a transcription factor and downstream target of mTOR pathway, which has been shown to be activated in epilepsy." (PMID 26217188, 2015). "Moreover, mTOR pathway activation has been reported as less evident or absent in FCD I or histologically-normal cortex in epilepsy." (PMID 25005575, 2014). "Recent studies, however, have demonstrated mTOR pathway activation in HS in epilepsy, suggesting that it may not be a specific biomarker for FCDIIb or TSC alone." (PMID 25005575, 2014). "In this study, we investigated the effects of vigabatrin on epilepsy in a knock-out mouse model of TSC and tested the novel hypothesis that vigabatrin inhibits the mammalian target of rapamycin (mTOR) pathway, a key signaling pathway that is dysregulated in TSC." (PMID 23437388, 2013). "This dual regulatory capacity may represent a TSC‐specific mechanism, as such combined effects on both mTOR‐driven cell signaling and electrophysiological excitability have not been reported in other epilepsy subtypes, such as temporal lobe epilepsy, where mTOR signaling remains largely intact." (PMID 41090516, 2026).
epilepsy (continued). "However, no direct role of MTOR-related ciliopathy in epilepsy has yet been established." (PMID 40529445, 2025). "While mTOR inhibition has shown antiepileptogenic effects in preclinical models with hyperactivation of this pathway, such as tuberous sclerosis complex and certain focal cortical dysplasias, other studies have reported no protective effect in different epilepsy models." (PMID 40943279, 2025). "In a study with TSC1 knockout rats, severe epilepsy occured in adult rats without obvious changes in brain structure, suggesting that enhanced mTOR signaling may contribute to epileptogenesis through unknown mechanisms rather than structural changes in brain tissues." (PMID 37221133, 2023). "In seizure disorders such as TSC and NPC that are characterized by autophagy dysregulation, increase in normal tau levels may in turn contribute to both seizure activity and PTEN inhibition, creating a feedback loop of mTOR overactivation that results in further hyperphosphorylation of tau." (PMID 35923547, 2022). "Although granule cell mossy fiber sprouting is not required to produce epilepsy in mTOR hyperactivation models, increased sprouting of granule cells may contribute to epilepsy progression in the animals by promoting the formation of recurrent excitatory circuits." (PMID 24672426, 2014). "Everolimus, an mTOR inhibitor, has shown the ability to reverse social behavior deficits in TSC2 mice without an additional epilepsy model." (PMID 35422816, 2022). "Short-term everolimus before epilepsy surgery in TSC and FCD resulted in no adverse events and trending lower mTOR signaling (phospho-S6)." (PMID 35587487, 2022). "Although no clear relationship between GPC1 and epilepsy has been described, another member of the same proteoglycan family, GCP4, has been reported to promote mossy fiber sprouting after pilocarpine-induced status epilepticus via mTOR." (PMID 40076950, 2025). "In addition, the mTOR pathway genes RPS6, TPI1, ENO1, and PGK1 are enriched in PY2-like cortical neurons of brain samples from patients with epilepsy compared with people in a nonepilepsy control group." (PMID 40026248, 2025). "In nonneuronal cells, mTOR is known to regulate activity, cellular localization, and the level of several transcription factors, e.g., hypoxia-inducible factor 1α (HIF-1α), increased expression of which was reported in animal models of epilepsy." (PMID 26993296, 2017). "In addition, there is strong evidence that rapamycin may prevent epilepsy and ameliorate its progression in mice lacking the tuberous sclerosis complex genes 1 and 2 (TSC1/2), which act as negative regulators of mTOR." (PMID 24062645, 2013).
tuberous sclerosis (347 papers, 2005 to 2026). Hereditary disease characterized by seizures, intellectual disability, developmental delay, and skin and ocular lesions. "Tuberous sclerosis complex is associated with dysregulation of the mammalian target of rapamycin (mTOR) signaling pathway, leading to abnormal vascular smooth muscle proliferation, structural vessel wall weakness, and predisposition to aneurysm formation." (PMID 42037827, 2026). "The main cause of tuberous sclerosis complex is the overactivation of the mTOR pathway due to the inactivation of the TSC1-TSC2 complex." (PMID 39901197, 2025). "Mutations in TSC1 and TSC2, which cause tuberous sclerosis complex, disrupt mTOR signaling, leading to neuronal dysregulation, epilepsy, and an increased risk of tauopathy." (PMID 41179085, 2025). "mTORopathies represent a group of neurodevelopmental disorders linked to dysregulated mTOR signaling, resulting in conditions such as tuberous sclerosis complex, focal cortical dysplasia, hemimegalencephaly, and Smith–Kingsmore Syndrome." (PMID 40358185, 2025). "Medication: In cases involving specific tumor types, such as multiple cardiomyomas linked to tuberous sclerosis complex, mTOR inhibitors like sirolimus can be administered to control tumor growth and alleviate arrhythmias." (PMID 40741386, 2025). "Recently, a mammalian target of rapamycin (mTOR) inhibitor effectively treated rhabdomyomas associated with tuberous sclerosis." (PMID 40490815, 2025). "Tuberous sclerosis (TS) is a progressive neurodevelopmental disorder caused by mutations in Tsc1 or Tsc2 genes, leading to hyperactivity of the mTOR pathway." (PMID 39192595, 2024). "Two-hit (one germline and one somatic) loss of function mutations in repressors of the mTOR pathway have similar outcomes and can result in tuberous sclerosis complex." (PMID 39457364, 2024). "There is a wider range of clinical application of mTOR inhibition in other mTOR pathway-linked diseases, especially tuberous sclerosis." (PMID 39687400, 2024). "Over-activation of mTOR and associated defective autophagy are linked with the development of seizures in children with focal cortical dysplasia and tuberous sclerosis complex." (PMID 37880579, 2023). "In particular we will discuss the use of kinase inhibitors in tuberous sclerosis, in RASopathies, and in ciliopathies associated with either the mTOR, the RAS, or the Wnt pathway, respectively." (PMID 36982349, 2023). "Hypervascularization is a feature of tuberous sclerosis complex lesions, and vascular abnormalities are evident in a variety of other disorders caused by mTOR pathway mutations." (PMID 36759189, 2023). "Mutations in mTOR pathway-related genes are associated with many genetic disorders such as tuberous sclerosis, focal cortical dysplasia, and megalencephaly." (PMID 36989136, 2023). "In detail, it has been known that alterations of the mTOR pathway are implicated in the pathogenesis of renal tumors arising in patients affected by the inherited tuberous sclerosis syndrome such as renal angiomyolipoma and related lesions and TSC-RCC." (PMID 37938323, 2023). "Excessive mTOR signaling through a mutation in the tuberous sclerosis complex leads to hippocampal hyperexcitability linking mTOR with temporal lobe epilepsy." (PMID 37880579, 2023). "This drug is beneficial for the treatment of seizures in animal models of genetic mTOR hyperactivation and in patients with tuberous sclerosis complex (TSC) caused by TSC2 or TSC1 mutation leading to mTOR hyperactivation." (PMID 35040598, 2022). "Heterozygous mutations in either TSC1 or TSC2 that form an MTOR-inhibiting complex can cause tuberous sclerosis by hyperactivating MTOR signaling." (PMID 34200511, 2021). "Activation of mTOR signaling causes diseases with severe neurological manifestations, such as tuberous sclerosis complex and focal cortical dysplasia." (PMID 34381067, 2021).
tuberous sclerosis (continued). "Currently, a novel mTOR inhibitor, LY3023414 is administered in pediatric patients carrying targetable mutations of the TSC (Tuberous sclerosis complex)/PI3K/mTOR pathways (NCT03213678)." (PMID 33917001, 2021). "Since the loss of NF1 also causes hyperactivation of the PI3K-AKT-mTOR pathway, mTOR inhibitors (everolimus) have been used in clinical trials with very positive responses for LGGs in children with tuberous sclerosis." (PMID 34073340, 2021). "Particularly, pathogenic variants in TSC1 that inhibit MTOR activity underlies the Tuberous Sclerosis Complex (TSC)." (PMID 33071758, 2020). "Among these, TSC1 or TSC2 characterizes rare subependymal giant-cell astrocytomas in patients with tuberous sclerosis, causing aberrant activation of mTOR." (PMID 33747896, 2020). "Activation of the mTOR pathway has also been associated with the neuropathological phenotype of tuberous sclerosis complex (TSC), a rare autosomal dominant genetic disease that features astrogliosis and seizures." (PMID 33204597, 2020). "Tuberous sclerosis (TSC) is a multisystem autosomal dominant genetic disorder due to loss of function of TSC1/TSC2 resulting in increased mTOR (mammalian target of rapamycin) signaling." (PMID 32973442, 2020). "mTOR activation is essential and sufficient to cause polycystic kidneys in Tuberous Sclerosis Complex (TSC) and other genetic disorders." (PMID 32581239, 2020). "It was also found to be regulated in a whole exome sequencing screen for cancer gene alterations by mTOR-activated tuberous sclerosis complex-associated renal cell carcinoma." (PMID 32146539, 2020). "Dysregulation of mTOR signaling was found to underlie the development of subependymal giant cell astrocytomas in tuberous sclerosis, which provided a basis for logical strategies for mTOR-directed molecular-targeted therapy." (PMID 32375301, 2020). "In recent years, sequencing efforts have linked rare genetic disorders like Tuberous Sclerosis Complex (TSC) to hyperactivated PI3K/mTOR signaling." (PMID 31752127, 2019). "One of the genes fallen into three categories examined, TSC2 (tuberous sclerosis 2), a key regulator of mTOR signaling, causes tuberous sclerosis." (PMID 31847491, 2019). "Hyperactivated mTOR signaling in the developing brain has been implicated in multiple forms of pathology including tuberous sclerosis complex (TSC)." (PMID 28588230, 2017). "Akt inhibits the activity of the TSC1/TSC2 (proteins harboring mutations in tuberous sclerosis) complex, a negative regulator of mammalian target of rapamaycin (mTOR), which regulates autophagy." (PMID 27911875, 2016). "Recent study mentioned that mTOR inhibitor was effective in PEComa associated with tuberous sclerosis because of mTOR pathway upregulation." (PMID 27307283, 2016). "In the nervous system, increased activity of mTOR has been associated with neurofibromatosis type 1, tuberous sclerosis, Lhermitte-Duclos disease, and GBM." (PMID 26120474, 2015). "For example, inactivating mutations in the gene TSC1 result in upregulation of mTOR and cause the disease Tuberous Sclerosis Complex." (PMID 25593991, 2014). "This is notable since mutations of single genes often associated with ASD clinical features also have aberrant mTOR signaling including Fragile X, tuberous sclerosis, PTEN, and neurofibromatosis." (PMID 24007566, 2013). "Mutations in tuberous sclerosis genes result in a constitutive activation of the mammalian target of rapamycin (mTOR) and the drug sirolimus (also known as rapamycin) suppresses such mTOR signaling." (PMID 23628229, 2013). "Dysregulation of mTOR signaling has been implicated in various neuropathological disorders including cortical dysplasia, tuberous sclerosis, and neurodegenerative disorders such as Alzheimer’s disease." (PMID 22761730, 2012). "Tuberous sclerosis is caused by mutations in the Tuberous sclerosis complex 1 or 2 genes, which in turn regulates mechanistic target of rapamycin- (mTOR) dependent translation." (PMID 21984899, 2011).